RNU6-1269P (RNA, U6 small nuclear 1269, pseudogene)
Gene: Small nuclear RNA gene on chromosome 9 (40,233,923 to 40,234,029, forward strand). Ensembl gene ENSG00000212441.
Homologues: Orthologues: chimpanzee U6 (99% identical), macaque U6 (93% identical), dog U6 (70% identical), mouse Gm54642 (61% identical), mouse Gm22279 (59% identical), rat LOC120101210 (58% identical). Paralogues in human: RNU6-1193P (100% identical), RNU6-368P (100% identical), RNU6-538P (100% identical), RNU6-1320P (99% identical), RNU6-599P (99% identical), U6 (97% identical), U6 (96% identical), RNU6-316P (95% identical), RNU6-55P (95% identical), U6 (95% identical), RNU6-954P (94% identical), RNU6-821P (87% identical), and 1288 more.